NF1 (neurofibromin 1)
Diseases named in the same sentence as NF1 in open-access papers (continued):
Sharing a sentence is not in itself a finding about the gene and the disease.
neurofibroma (continued). "Our long-term experience suggests that the multidisciplinary team-based surgical approach should be adopted to provide comprehensive individualized care to patients with NF-1 and warrants its substantial role in treating the patients with complicated plexiform neurofibromas." (PMID 35455674, 2022). "Given the key role of abnormal RAF/MEK/ERK pathway signaling in neurofibromas, a phase I study of selumetinib (a MEK inhibitor) in children/young adults with NF1-related inoperable plexiform neurofibromas has demonstrated a median maximal decrease of 24% in the volume of the tumors." (PMID 36358751, 2022). "In the present study, we addressed the still challenging issue of whether the environmental niche is determinant for NF1 DI SC progression toward tumorigenesis and thus for neurofibroma onset." (PMID 34066061, 2021). "In addition, notable divergence can be observed in the occurrence of various neurofibromas among the atypical NF1 microdeletion patients." (PMID 34168676, 2021). "Several studies have shown that certain NF1 mutations give rise to CALMs and freckling only phenotypes without any visible neurofibromas." (PMID 34566848, 2021). "Additionally, it was reported that inhibition of the RAS-downstream effector mitogen-activated protein kinase (MEK) kinase in the Nf1flox/flox; DhhCre mouse model of NF1 hampered the growth of neurofibroma in 80% of mice." (PMID 34359780, 2021). "In regard to NF1, we hypothesize that anti-IL-4 receptor monoclonal antibody dupilumab may inhibit the growth of neurofibromas, interfering with IL-4 and IL-13 binding to type I and type II receptors expressed on mast cells and fibroblasts." (PMID 34275694, 2021). "Patients with NF1 microdeletions tended to develop more severe phenotypes that manifest as learning disabilities, facial dysmorphism, cardiovascular anomalies, increased numbers of neurofibromas, and malignant peripheral nerve sheath tumors." (PMID 34988040, 2021). "They appear earlier than neurofibromas and multiple Lisch nodules are specific to NF1." (PMID 33530415, 2021). "The negative correlation between missense variants and neurofibromas is especially interesting, suggesting a potentially lower impact of partial loss of function in the pathogenesis of these NF1 features as compared to complete protein deficiency." (PMID 33919865, 2021). "Previous studies established an early-onset of neurofibromas among NF1 microdeletion patients." (PMID 34168676, 2021). "The natural history of sporadic MPNSTs is also distinct—sporadic MPNSTs typically arise de novo rather than from a pre-existing plexiform neurofibroma, and they occur in patients 25–30 years older than patients with NF1-associated MPNSTs." (PMID 33707600, 2021). "Additionally, therapies such as imatinib, shown to be highly effective at attenuating plexiform neurofibroma growth in mouse models of NF1, have exhibited far less efficacy for treating human NF1-associated plexiform neurofibromas." (PMID 34630515, 2021). "As in plexiform neurofibromas, many MPNSTs have biallelic inactivation of the NF1 gene." (PMID 33808166, 2021). "Somatic second hit NF1 PVs are typically identified in every NF1-associated tumor such as cutaneous and plexiform neurofibromas as well as in tissues from distinctive nontumor lesions such as CALMs,37 thereby resulting in biallelic NF1 activation." (PMID 34012067, 2021). "Ras hyperactivation, caused by loss of NF1, does not result in the malignant transformation of neurofibromas." (PMID 33808166, 2021).
neurofibroma (continued). "In support of the dual targeting of AXL and MEK1/2, NF1–associated MPNSTs with ERK activation grow more rapidly than do those without ERK activation, suggesting that MEK signaling is an early event in the transformation of neurofibroma into MPNST." (PMID 33283192, 2020). "A high NF-1 score warrants screening for internal neurofibromas by imaging (preferably by MRI)." (PMID 32014052, 2020). "Recent research has shown that FDG-PET scans can be helpful in distinguishing malignant from benign lesions, differentiating MPNSTs from neurofibromas with an 80% specificity and almost 100% sensitivity, which is why an NF1 consensus does recommend performing it." (PMID 32189989, 2020). "Mice heterozygous for an NF1-knockout mutation (Nf1+/–) do not develop neurofibromas, MPNST, or other hallmark features of NF1, and studies have proposed mismatch repair genes as modifier genes in NF1 tumor development." (PMID 32814709, 2020). "Furthermore, our results indicate a high frequency of cutaneous and subcutaneous neurofibromas in children and adolescents with NF1 microdeletions." (PMID 32533297, 2020). "NF1 is downregulated (lower expression) in the knockdown and knockout studies, and upregulated (overexpressed) in the evaluation of malignant tumors when compared to benign neurofibromas." (PMID 32858845, 2020). "When we examined the expression of the selected miRNAs in an unrelated series of unpaired fresh frozen plexiform neurofibroma, atypical neurofibroma and NF1-derived MPNST samples the down or upregulation of most selected miRNAs could not be firmly established." (PMID 32076030, 2020). "The MSI2 score in NF1-MPNSTs was significantly higher than the score in neurofibromas." (PMID 32606289, 2020). "We first determined whether MSI2 expression was significantly higher in NF1-MPNSTs than it was in neurofibromas through analysis of two MPNST patient cohorts, Jessen_cohort (GEO: GSE41747) and Kolberg_cohort (GEO: GSE66743)." (PMID 32606289, 2020). "Therefore, individuals with NF-1 are vulnerable to developing low-grade tumors, such as neurofibromas and Lisch nodules; however, they are often undetectable in early childhood and do not reach maximum frequencies until adulthood." (PMID 32733046, 2020). "One out of eight NF1+/ex42del minipigs developed a detectable neurofibroma." (PMID 32193437, 2020). "However, there are still some shortcomings in this study: NF1-MPNSTs are a kind of malignant transformation that originate from neurofibromas." (PMID 32606289, 2020). "Plexiform neurofibromas are uncommon and occur in almost 5–15% patients with NF-1." (PMID 32913647, 2020). "In addition, a SOS1 mutation was identified in two familial cases with previous clinical diagnosis of NF1 and multiple spinal nerve enlargements resembling plexiform neurofibromas." (PMID 32575496, 2020). "MRI of orbit was suggestive of NF-1 with right orbital plexiform neurofibroma." (PMID 32913647, 2020). "Thus, these Schwann cells made from a NF1−/− iPSC represent a valuable model to study and treat plexiform neurofibromas." (PMID 32353955, 2020). "However, the MEK inhibitor selumetinib has shown promise in clinical trials treating NF1-mutant neurofibromatosis and plexiform neurofibroma patients." (PMID 31285545, 2020). "Finally, we believe that combinatorial targeted treatment approaches will also have applicability to NF1-related plexiform neurofibromas and atypical neurofibromas." (PMID 31427883, 2019). "With clinical exclusion of NF-1, she was determined to have a solitary neurofibroma." (PMID 29426349, 2018). "Neurofibromas are one of the most common and characteristic clinical manifestations of NF-1." (PMID 29849532, 2018). "The first mouse model of NF1 was a traditional germ line heterozygous knockout mouse, which developed some of the less common NF1-associated tumors, however, did not develop neurofibromas or other characteristic symptoms of NF122,23." (PMID 30302402, 2018).
neurofibroma (continued). "However, other investigators described mouse models where neurofibromas are much less dependent on the Nf1+/− microenvironment." (PMID 30479396, 2018). "Spinal deformity in patients with NF-1 can be induced by localized neurofibromas." (PMID 30408738, 2018). "Therefore, this genetically engineered mouse (GEM) neurofibroma model allows monitoring of changes downstream of Nf1 loss/elevated RAS-GTP specifically in SCs, over time, in a predictable model of benign neurofibroma formation." (PMID 28256556, 2017). "Further, patients with type-1 NF1 microdeletions exhibited a variety of features that were markedlymore frequent than in the general NF1 population including intellectual disability,high numbers of subcutaneous and spinal neurofibromas, and the occurrence ofplexiform neurofibromas." (PMID 28213670, 2017). "There were no other NF1-associated clinical symptoms like skinfold freckling, Lisch nodules and neurofibromas has been identified." (PMID 27980226, 2017). "Nf1−/− SCs must initiate tumorigenesis, as they are the only Nf1−/− cells present in neurofibromas, but neurofibroma macrophages may maintain the pro-inflammatory state in the neurofibroma microenvironment, accounting for prolonged chronic inflammation." (PMID 28256556, 2017). "MPNST or plexiform neurofibromas without other symptoms of NF1, i.e. sproradic tumors, are probably caused by somatic mosaicism for an NF1 mutation." (PMID 29179472, 2017). "Importantly, this situation differs on the genomic level from plexiform neurofibroma, in which NF1 is considered to be a more isolated driver, and where MEK-inhibition has shown promise as a single agent." (PMID 29118384, 2017). "Heterozygous inheritance of a defective Nf1 gene leads to a wide variety of clinical pathologies including café-au-lait macules, axillary freckling, Lisch nodules, cognitive disorders, bone deformities, and neurofibromas." (PMID 27494873, 2016). "No spontaneous or NF-1 associated neurofibromas (0/35), schwannomas (0/11), or normal nerves expressed NY-ESO-1." (PMID 27655679, 2016). "The subsequent demonstration that development of neurofibromas in mouse models required Nf1 haploinsufficiency in myeloid cells of the tumor microenvironment established the central role of these bone marrow-derived cells in the pathogenesis of NF1." (PMID 27448806, 2016). "Although these latter changes, associated with gadolinium-enhanced deep nodules evoking neurofibromas, are typical findings of NF1, our subject presented no NF1 gene mutations." (PMID 25884655, 2015). "This investigation maybe would have enabled us to shed some light on what happens in the neurofibroma at both NF1 loci." (PMID 25580325, 2014). "However, there were no NF1 microdeletions in the DISC and REP1 cohorts, nor did we detect the 3-basepair in-frame deletion (NM_000267.3:c.2970_2972delAAT) of exon 22 (legacy exon 17), an NF1 genotype know to affect neurofibroma number." (PMID 25329635, 2014). "Individuals with NF-1 have a significantly increased risk of developing MPNSTs frequently arising in preexisting neurofibromas which are uncommon in those without NF-1." (PMID 25317349, 2014). "Neurofibroma of the appendix is extremely rare, even in patients with NF1." (PMID 25295078, 2014). "Neurofibroma may be a manifestation of neurofibromatosis type 1 (NF-1) and the probability of recurrence in neurofibroma is higher than schwannoma." (PMID 24507572, 2014). "In these genetically engineered mouse strains, loss of Nf1 gene expression in neoplastic Schwann cell or neuroglial progenitors alone is not sufficient for plexiform neurofibroma or optic glioma formation, respectively." (PMID 25243094, 2014). "Using a family-based association test, a single SNP (rs2151280) in ANRIL was significantly associated with the number of plexiform neurofibromas in a cohort of 740 NF1 patients, but not in a cohort of 29 individuals with a microdeletion of NF1." (PMID 25329635, 2014).
neurofibroma (continued). "We add to this evidence by showing that shRNA-mediated NF1 knockdown renders two oncogenic ALK-driven human neuroblastoma cell lines resistant to pharmacological ALK inhibition, and by confirming that ALK mRNA is expressed in neurofibroma-derived NF1−/− human Schwann cells." (PMID 24278035, 2013). "The molecular mechanisms responsible for malignant transformation of neurofibromas in NF1, and those involved in tumor progression for the development of sporadic or NF1-associated MPNST, are largely unknown." (PMID 24303016, 2013). "Plexiform neurofibroma is usually recognised as a pathognomonic criterion of NF-1 (or Von Recklinghausen’s disease); it may also occur as a solitary lesion arising in a nerve root." (PMID 23653673, 2013). "Genomic abnormalities, other than those at the neurofibromin 1 (NF1) locus, have rarely been detected in benign neurofibromas but are numerous in MPNSTs suggesting that many secondary genetic changes are required for the transformation from a benign neurofibroma to MPNST." (PMID 23319880, 2012). "Loss of heterozygosity (LOH) in the inherited wild-type allele has been detected in some tumor types in NF1 patients, although it has been demonstrated that heterozygosity for NF1 is a key element for the development of many NF1 symptoms, including neurofibroma formation." (PMID 22550514, 2012). "Indeed, neurofibromas are composed of an aggregation of multiple cell types and they are infiltrated by surrounding hypermotile Nf1+/− mast cells (which secrete mediators that remodel the extracellular matrix and initiate angiogenesis)." (PMID 23082153, 2012). "Recently, an elegant study showed that NF1+/− SKPs could form neurofibromas in a conditional mouse model, although a key role for tumor environment was also found." (PMID 22550514, 2012). "It is known that the other 50% of patients affected by neurofibromas have no family history of the disease; their NF1 is sporadic and perhaps results from a new mutation in the germ cell of one of the parents." (PMID 21838856, 2011). "Our working hypothesis is that genes influencing the rate and efficiency of these mechanisms are key factors of neurofibroma development, because somatic inactivation of the NF1 gene is a necessary and limiting step in dNF development." (PMID 21031597, 2011). "In general, sporadic neurofibromas are histologically identical to those seen in NF1." (PMID 20858283, 2010). "Neurofibromas of the breast are quite rare manifestations of patients with NF1." (PMID 20205809, 2010). "The COSMIC database also lists mutations in NF1 in multiple MPNSTs, colorectal carcinoma, and of course in neurofibromas, but none yet in liposarcoma." (PMID 18784837, 2008). "FMGCs have been described in gynaecomastia and neurofibroma in NF1." (PMID 18067673, 2007). "In one of these series, neurofibromas alone were the most common manifestation of segmental NF-1." (PMID 15363097, 2004). "The location of the current patient's neurofibroma is also somewhat unusual for segmental NF-1." (PMID 15363097, 2004). "Further in vivo studies may determine whether systemic administration of AAV-GRDC24 can rescue differentiating Schwann cell precursors with complete somatic NF1 inactivation in NF1 patients during neurofibroma formation, potentially preventing future tumors and treating existing ones." (PMID 41022755, 2025). "Neurofibromatosis type 1 (NF-1) is an autosomal dominant neurocutaneous disorder characterized by skin abnormalities, such as café-au-lait macules and skinfold freckling, as well as peripheral nerve sheath tumors such as neurofibromas, schwannomas, and various other tumors." (PMID 40416267, 2025). "Furthermore, NF1−/− SCs exhibit superior pro-inflammatory transcriptional programs, producing various inflammatory cytokines and paracrine factors that mediate immune cell recruitment to the neurofibroma site." (PMID 40940747, 2025).
neurofibroma (continued). "Plexiform neurofibromas also have lower basal oxidative stress compared to MPNSTs, which may help explain our findings that plexiform neurofibroma and NF1-patient derived Schwann cells show an IC50 for ARS and DHA that is very similar to that of normal Schwann cells." (PMID 40724874, 2025). "Hence, mutually exclusive bi-allelic loss-of-function mutations in the PRC2 core proteins SUZ12 and EED are recurrently observed in NF1-associated MPNSTs, while not observed in the pre-cancerous tumours, neurofibromas." (PMID 38448973, 2024). "Likewise, skin injury also accelerates the development and growth of cutaneous neurofibromas in Nf1-mutant mice, associated with increased Ccl2 and Ccl5 expression, while partial sciatic nerve transection induces the formation of neurofibromas in Nf1-mutant mice at the site of the injury." (PMID 38308315, 2024). "The lack of neurofibromas in this cohort is similar to our previously reported cohorts of p.Met992del, p.Met1149, and p.Arg1809 missense variants, all of which have a milder phenotype compared to the classic NF1 population." (PMID 39001468, 2024). "Neurofibromas are the most common neoplasms associated with NF-1, but malignancies such as MPNST, non-lymphocytic leukemias, gliomas, pheochromocytomas, and gastrointestinal stromal tumors may also develop." (PMID 38013269, 2023). "In addition, no NCSCs were identified in normal adult peripheral nerves or the regions that develop neurofibroma, and no tumorigenicity due to Nf1 loss in NCSCs was observed." (PMID 36139671, 2022). "There was a notable absence of all NF1-associated tumour types (neurofibroma and glioma)." (PMID 34897289, 2022). "Our findings indicate that tumor progression induced by SHP-2 (G503V) and its suppression by BRAP (G370A) may provide the basis for the development of new strategies for the treatment of NF1-MPNST as well as for the prevention of the malignant transformation of neurofibroma in individuals with NF1." (PMID 35625983, 2022). "Missense mutations affecting residue p.Arg1809 in NF1 were associated to a mild phenotype characterized by multiple café au lait spots, learning disabilities, short stature, and pulmonic stenosis but absence of neurofibromas." (PMID 35885913, 2022). "MPNSTs represent about 5% of all sarcomas and may arise from a peripheral nerve or a pre-existing neurofibroma; in about 50% of cases, these tumors arise in the context of NF1, while in the remaining cases they appear to be sporadic (40% of cases) or associated with a previous history of radiation." (PMID 35741273, 2022). "However, we failed to acquire the medical record of neurofibroma, NF1 germline mutation associated tumor, in their families." (PMID 35372080, 2022). "The authors genetically deleted Nf1 (a RasGAP protein) to activate all Ras proteins in vivo followed by examination of mice double-deficient in a specific Ras protein and Nf1 to assess its requirement in the generation of TGF-β-dependent neurofibromas that arise in Nf1-null mice." (PMID 33478130, 2021). "Neurofibromas are complex tumors originating from the peripheral nerve sheath, composed of Schwann cells (SCs) undergoing loss of heterozygosity (LOH) at the NF1 locus in an NF1+/− milieu composed by many other NF1 haploinsufficient (HI) cells, including mast cells, macrophages and myofibroblasts." (PMID 34066061, 2021). "Besides the two, the missense variant c.3112A>G, p.Arg1038Gly of NF1 gene, tested in seven patients from two unrelated families, is also associated with CALMs without other types of neurofibromas." (PMID 34566848, 2021). "In order to confirm whether CNFs and PNFs are genomically and transcriptomically distinct lesions using advanced sequencing techniques, we compared publicly available RNA-seq data from an NF1 test cohort where cutaneous/non-plexiform neurofibromas were compared to PNFs." (PMID 33436083, 2021).